SOCS3 (suppressor of cytokine signaling 3)
Diseases named in the same sentence as SOCS3 in open-access papers (continued):
Sharing a sentence is not in itself a finding about the gene and the disease.
infection (continued). "Virus mediated SOCS-3 gene induction at early stages of infection appeared to occur concomitant with an immediate and strong induction of IFNβ." (PMID 18989459, 2008). "While SOCS-3 mRNA is strongly and transiently elevated in the early phases of infection, SOCS-1 gene transcription is only significantly induced 15 h p.i.." (PMID 18989459, 2008). "In contrast, infection of SOCS-3 knock out cells resulted in strongly elevated phosphorylation of STAT1 in a sustained fashion." (PMID 18989459, 2008). "Instead we observed a significant up-regulation of SOCS-3 by viral 5′ triphosphate RNA, indicating that gene induction occurs via accumulation of vRNA during infection." (PMID 18989459, 2008). "Here we present data, showing that RNA-induced expression of SOCS-3 in early phases of infection leads to a functional inhibition of IFN-induced STAT activation and gene expression." (PMID 18989459, 2008). "SOCS3, specifically, is upregulated post-infection by the Newcastle disease virus, duck hepatitis virus type 1, and porcine reproductive and respiratory syndrome virus (PRRSV), being exploited by these viruses to evade host immune surveillance and boost viral replication." (PMID 40872795, 2025). "SOCS1 and SOCS3 are typically induced by coronaviruses in early‐stage infection." (PMID 40844207, 2025). "Infection with psarA:gp130 also led to significantly lower SOCS3 abundance compared to psarA." (PMID 40188438, 2025). "In the study of bone marrow regeneration, a common host immune response following infection, it was discovered that Adar1 promotes infection-induced bone marrow regeneration by binding to and disrupting the stability of Socs3 mRNA in an RNA editing-independent manner." (PMID 41488000, 2025). "A notable increase in SOCS3 protein levels across all treatment groups, particularly in the combination group, indicates a possible mechanism for boosting macrophage function in eliminating infection." (PMID 40855340, 2025). "In the current study, significant upregulation of SOCS3 in the caecum, liver, and spleen of birds challenged with Salmonella Gallinarum likely indicates an attempt to moderate the inflammatory response against infection." (PMID 39963274, 2025). "Furthermore, in the post-infection assays (cells infected and post-treated), the relative expression of SOCS3, IL-10, and IFN-γ was significantly upregulated." (PMID 38791551, 2024). "Moreover, in the post-infection assays (cells infected and further treated), the mRNA levels of SOCS3, IL-10, and IFN-γ were significantly (p < 0.05) upregulated, whereas STAT1 was downregulated." (PMID 38791551, 2024). "Furthermore, in the post-infection assays with rotavirus and C. sorokiniana, we observed a significant (p < 0.05) relative expression of SOCS3, STAT1, and STAT2." (PMID 38791551, 2024). "Our results suggested that the increased expression of SOCS3 during infection might promote the ubiquitination degradation of IDO and ultimately lead to the decrease of IDO protein levels." (PMID 38822095, 2024). "SOCS3 has also been reported to be a major regulator in inflammation and infection." (PMID 37793095, 2024). "SARS-CoV-2 suppresses the host immune response by activating SOCS1 or SOCS3 early in infection." (PMID 38792727, 2024). "We also confirmed this biphasic increase of SOCS3 expression at the transcription level, in which SOCS3 mRNA level quickly peaked at 4hpi, dropped at 8 hpi, and trended up again slowly till the end of the infection cycle." (PMID 36753521, 2023). "In addition, treating NPCs with HCMV replication inhibitors (phosphonoacetic acid [PAA] and ganciclovir [GCV]) greatly reduced the infection-induced SOCS3 protein level change compared to the control." (PMID 36753521, 2023). "We further investigated the effect of TP infection in macrophages using knockdown and overexpression experiments of m6A-related proteins and examined the changes in the gene expression profiles and impact of SOCS3 expression." (PMID 35444649, 2022).
infection (continued). "On the contrary, PCV2 enhances the expression of the suppressor of cytokine signaling 3 (SOCS3), which further interacts with STAT3 and TNF-associated receptor-associated factor 2 (TRAF2), resulting in subclinical infection characterized by downregulation of IL-6 and TNF-α signaling." (PMID 35891399, 2022). "Similarly, socs-3 was observed to peak at 9 h and gradually decreased to lower expression levels at 48 h post-infection." (PMID 35328519, 2022). "Furthermore, SOCS3 activation is usually observed following infection and plays a tissue protecting role against inflammation side effects." (PMID 33226440, 2021). "In MKN1 cells, which have low expression of SOCS3 after infection of T-01, T-SOCS3 infection promoted SOCS3 expression, while T-SOCS3 could replicate and induce a more potent oncolysis in comparison with T-01." (PMID 33659045, 2021). "Moreover, the changes in protein expression were also interpreted by the FI, and the results showed that expression of SOCS3 was highly maintained in T. gondii–infected brain during the 12 weeks of infection." (PMID 33205383, 2021). "Densitometric analysis identifies the ratio of SOCS1/SOCS3 as 3:2 post one hour of infection." (PMID 35011356, 2021). "The other significant gene, SOCS3 is a major regulator of inflammation and infection." (PMID 33833401, 2021). "In the current study, we suggested that SOCS3 was downregulated by infection of T-01 in MKN1 cells." (PMID 33659045, 2021). "To confirm this hypothesis, we induced moDCs with TNFα to analyze its capacity to induce SOCS3 mRNA expression and, additionally, we blocked TNFα in DCs using a neutralizing antibody prior to infection." (PMID 33023610, 2020). "This raises the question whether p38 phosphorylation and SOCS3 expression are stimulated by a specific cytokine milieu created immediately upon infection with H. pylori wt." (PMID 33023610, 2020). "We could, for example, verify that expression of IL10 or SOCS3 genes is reduced during the infection or that expression of STAT4, LAMP3, ADORA2A and BIRC3 genes peaks 6 h pi." (PMID 32070192, 2020). "To determine how H. pylori induces SOCS3 expression within 1 h of infection, we first investigated whether activation of TLRs might contribute to this gene activation." (PMID 33023610, 2020). "Having shown that H. pylori induces the expression of SOCS3 within the first hour post infection, we analyzed whether the presence of SOCS3 affects H. pylori-induced activation of human DCs." (PMID 33023610, 2020). "To test whether these kinases are potential inducers of SOCS3 in DCs, we blocked p38 and MEK1/2 prior to infection and monitored SOCS3 expression 1 h post infection." (PMID 33023610, 2020). "Thus, HIV-1 downregulates SOCS3 in early phase of infection to promote inflammatory responses for large production of activated cells which are suitable for viral spread and induces SOCS3 later on to limit inflammatory responses and ensure viral survival." (PMID 30766526, 2019). "In addition to the viruses featured in these reviews, more herpesviruses also are now known to stimulate SOCS1 and/or SOCS3 during in vitro or in vivo infection." (PMID 31031749, 2019). "Interestingly, there existed a cytokine-independent mechanism of the robust induction of SOCS3 by IAV at early stages of the infection." (PMID 31474976, 2019). "Similarly, the target genes of MERTK activation, the cytokine suppressors SOCS1 and SOCS3, were also increased after P strain infection, in addition to IRF-1, that regulates type I IFN levels, which were higher with C#1 compared with P strain infection." (PMID 31695702, 2019). "Taken together, these data indicate that IAV itself, but not IAV-induced cytokines including IL-6 or newly synthesized viral proteins, might trigger SOCS3 expression at the early infection stage." (PMID 31474976, 2019).
infection (continued). "SOCS3-mediated promotion of EBOV egress results in SOCS3 incorporation into EBOV virions; whether virion incorporation of SOCS3 enhances the infection of target cells remains to be determined." (PMID 30609802, 2019). "Because UV-inactivated MCMV failed significantly to stimulate SOCS1 and SOCS3 expression at early time points following infection of IC-21 mouse macrophages, we next investigated SOCS1 and SOCS3 mRNA expression later during MCMV infection (72 hpi) with or without the antiviral drug GCV." (PMID 28182772, 2017). "Following infection a significantly higher percentage of EdU‐positive cells, were found in the region defined by cell number 21–30, in HO‐VC compared to HO‐WT mice (p = 0.008), supporting an increase in IEC turnover in SOCS3 deficient intestine." (PMID 28508554, 2017). "Whatever the molecular mechanism explaining the inhibition of SOCS-3 expression during infection, it was probably not implicated during activation of HGEC by purified LPS-Pg." (PMID 28748038, 2017). "Therefore, MCMV-related stimulation of SOCS1 and SOCS3 occurred during infection of IC-21 mouse macrophages with the IE2-defective MCMV RM4503, suggesting that IE2 is dispensable for this phenotype." (PMID 28182772, 2017). "We have not eliminated the possibility, however, that this later stimulation of SOCS3 may be attributed to a second round of infection." (PMID 28182772, 2017). "The study sought to establish whether the infection of HGEC with live P. gingivalis would affect the mRNA expression of various genes potentially implicated in EGF signaling, mainly SOCS-3, IRF-1, EGF, EFGR, and STAT-3." (PMID 28748038, 2017). "Similarly as STAT3, SOCS3 is expressed in M. tuberculosis-infected human macrophages as early as 3 hours post-infection and remains highly detectable up to 24 hours post-infection." (PMID 27384401, 2016). "In the SIV-infected spleens, SOCS3 expression was shown to be highly expressed not only during acute infection but also throughout asymptomatic and chronic infection, demonstrating a strong potential reason for the suppression of IDO1 despite abundant virus stimuli during chronic infection." (PMID 28066416, 2016). "At 36 h post-infection, the cells were collected to analyze the efficacies of the SOCS3 siRNAs." (PMID 27581515, 2016). "and SOCS3 following an ex vivo LPS challenge suggests that an energy saving mechanism possibly exists in the intestine in the more feed efficient animals which impacts on their immune response to infection." (PMID 26840831, 2016). "These preliminarily results implied that viral proteins may be required to induce the upregulation of SOCS3 expression at early stages of infection." (PMID 25390684, 2014). "However, a tight regulation of SOCS3 expression in T cells is critical for determining the outcome of infection." (PMID 24600449, 2014). "Taken together, our data showed that JEV early infection could induce the upregulation of SOCS3 expression, both in vitro and in vivo, providing the basic theoretical foundation for future research on the invasion mechanism of JEV." (PMID 25390684, 2014). "Infection with mycobacteria enhanced the expression of SOCS3 in phagocytes." (PMID 24600449, 2014). "JEV early infection could induce SOCS3 expression, upregulating both the mRNA and protein levels in Raw264.7 cells in a time-dependent manner." (PMID 25390684, 2014). "However, Socs3 mRNA levels in pulmonary T cells before or after infection with BCG or M. tuberculosis were similar." (PMID 23853585, 2013). "In addition, adeno-sh-SOCS3 infection of primary calvarial osteoblasts resulted in a significant augmentation of MMP-13 gene expression induced by LPS stimulation when compared with cells infected with control virus (p < 0.05)." (PMID 23638389, 2013).
infection (continued). "Tnf mRNA and protein levels were reduced in M. tuberculosis- or BCG-infected gp130F/F BMM and were partially restored in gp130F/F Il-6−/− BMM, indicating that SOCS3 allows proper infection-induced TNF secretion in macrophages by hampering gp130/IL-6 receptor-mediated signalling." (PMID 23853585, 2013). "The level of induction of SOCS-3 by HSV-1 seems to determine whether infection turns to acute or persistent progression." (PMID 18989459, 2008). "Accordingly, infection of cells with the mutant virus resulted in a more pronounced and sustained, albeit delayed induction of SOCS-3 if compared to infection with the isogenic wild type, that is a very poor inducer of SOCS-3 but still reasonably well induces IFNβ." (PMID 18989459, 2008). "Indeed mRNA levels of all three representative ISGs were elevated in SOCS-3 knock out versus wild type cells at almost every time point during the course of infection." (PMID 18989459, 2008). "This prompted us to analyze whether SOCS-3 transcription might be induced due to an auto- or paracrine action of IFNβ expressed during infection." (PMID 18989459, 2008). "However, at the post-translation level, an increased expression of SOCS3 during infection could bind to the phosphorylated ITIMs of IDO, leading to its ubiquitination and degradation, ultimately resulting in decreased IDO expression." (PMID 38822095, 2024). "Some cells may express SOCS3 by infection of oHSVs, others may have downregulated SOCS3." (PMID 33659045, 2021). "However, later studies confirmed that IL-27Rα−/− mice developed normal Th1 response after infection, and IL-27 could induce IL-10 and SOCS3 to suppress Th1 cells, suggesting the bidirectional role of IL-27 in Th1 cells." (PMID 34299138, 2021). "Moreover, infection of human moDCs with H. pylori rapidly induces SOCS3 expression, which requires the type IV secretion system (T4SS), release of TNFα, and signaling via the MAP kinase p38, but appears to be independent of TLR2, TLR4, MEK1/2 and STAT proteins." (PMID 33023610, 2020). "As the effects of mock inoculating HFFs were not addressed in the protein analysis of SOCS3 and pSTAT3, it may be pertinent to perform cell associated infections with the same cell type to exclude effects of using different inoculating cells." (PMID 32038653, 2020). "This study revealed that infection with DHAV-1 strain CH60 is associated with enhanced type I and II interferon responses, activated innate immune responses, elevated levels of suppressor of cytokine signaling 1 and 3 (SOCS1 and SOCS3) accompanied with abnormalities in multiple metabolic pathways." (PMID 30197639, 2018). "Thus, these animals in which SOCS3 is deleted in DCs but not in inflammatory macrophages and neutrophils are also more susceptible to infection with M. tuberculosis." (PMID 29338039, 2018). "As SOCS1 and SOCS3 were induced by H5N1 virus in the initial round of viral replication at 6-h post infection, we next investigated if this cellular event could affect the expression of IFN-β after multiple rounds of influenza virus replication by infecting the cells using MOI of 0.001." (PMID 29475453, 2018). "In addition to this, a mutation (Tyr 1138 Ser) in tyrosine 1138 residue located in the intracellular domain of LEP-Rb isoform mediates STAT3/SOCS3 signaling, which results in decreased chemokine production and immune cells recruitment at the site of infection in mucosal gut tissue." (PMID 29868503, 2018). "Indeed, previous studies have demonstrated that S. suis induces upregulation of SOCS3 in mice and pigs following infection, with SOCS3 having been reported to block the catalytic site of JAK, thus inhibiting phosphorylation of STAT and suppressing IFNAR-induced effects." (PMID 28894449, 2017). "Therefore, increased IDO following infection may be partly due to increases in goblet cell number, but differences between HO‐VC and HO‐WT is likely to be due to increased IDO production in SOCS3 deficient animals." (PMID 28508554, 2017).
infection (continued). "Additionally, PCV2 infection of PK-15 cells that were treated with SOCS3 siRNAs exhibited elevated levels of IL-6 and TNF-α, compared with control cells, thereby demonstrating that PCV2 activated SOCS3 to minimize these proinflammatory responses to promote a subclinical infection." (PMID 27581515, 2016). "Thus, we presumed that PCV2 infection may manipulate SOCS3 to escape the host immune response, thereby leading to a subclinical infection." (PMID 27581515, 2016). "Although TNF secretion by infected SOCS3-deficient macrophages is reduced, TNF expression in the lungs of M. tuberculosis-infected Socs3fl/fl LysM cre mice was not diminished, suggesting that a role for TNF in the susceptibility to infection of Socs3fl/fl LysM cre mice is unlikely." (PMID 23853585, 2013). "SOCS3 expression in T cells can both obstruct the differentiation of inflammatory IL-17-producing Th17 cells and inhibit the secretion of anti-inflammatory IL-10 and TGF-β by T cells and mice with SOCS3-deficient T cells are more susceptible to infection with Leishmania major." (PMID 23853585, 2013). "Hence, the genes Ccl2, Ch25 h, Ifit3, Il1rn, Il6, Parp14, Ptx3, and Socs3 can be defined as a common core of genes expressed early in response to local infection and inflammation caused by Gram-negative stimuli." (PMID 21338499, 2011). "Finally, it should be stated that regardless whether SOCS-3 is additionally induced by type I IFNs at a later stage of infection, it is important that it can be induced earlier and in parallel to IFNβ directly by vRNA accumulation." (PMID 18989459, 2008). "The results of one previous study showed that SOCS3 expression was increased in liver tissues and PBMCs of ACHBLF patients and increased in livers of BALB/cJ mice 72 hours after infection." (PMID 40538651, 2025). "Comparing infection-induced TCRab+ T cells, adults exhibited higher average STAT3, SOCS1, and SOCS3 expression, whereas STAT1 and STAT2 were elevated in cells from infected children, highlighting divergent IFN signaling with age." (PMID 40834853, 2025). "Meanwhile, we observed that certain biomarkers (SLC7A5, PDE4D, CXCR4, PER1, PIK3R1, HBA1, HBB) were elevated during the pre-infection phase (LTBI), while others (SOCS3, GZMK, HIS1H3B) were upregulated in the post-infection phase (ATB)." (PMID 40589756, 2025). "In the case of West Nile virus (WNV) and tick‐borne encephalitis virus, infection results in transcriptional upregulation of SOCS1 and SOCS3, which suppress antiviral cytokine responses." (PMID 40844207, 2025). "IL6 and IL8 showed significant changes at 4 h post-infection (p-value = 0.0417 and p-value = 0.0115, respectively), while MCP1 and SOCS3 exhibited changes from 1 and 2 h post-infection, respectively (p-value < 0.05)." (PMID 40141288, 2025). "On the other hand, in the pre-infection assays with C. sorokiniana, the mRNA levels of SOCS3 and IFN-γ were increased, whereas in the post-infection assays, SOCS3, STAT1, and STAT2 were upregulated." (PMID 38791551, 2024). "To determine the effect of C. sorokiniana in HT-29 cells, we studied the mRNA levels of IFN-γ, IL-10, SOCS3, STAT1, and STAT2 genes in cells incubated with C. sorokiniana in the rotavirus pre- and post-infection assays." (PMID 38791551, 2024). "Therefore, our results indicated that SOCS3 could interact with IDO during infection." (PMID 38822095, 2024). "The infection of cells with oncolytic adenovirus CN305 (AdCN305)-SOCS3 and AdCN305 cell-penetrating peptides-SOCS3 (membrane permeable SOCS3) result in considerable cytotoxicity of liver tumor cells and downregulation of cyclin D1 and Bcl-xL." (PMID 35226171, 2023). "An additional four genes were upregulated in ΔprgH STm infection and were involved in the regulation of glycolysis (PFKFB3) and cytokine signaling (SOCS3), and intracellular signaling (RASD1, TRAF3IP2)." (PMID 37854334, 2023).